ERBB2 (erb-b2 receptor tyrosine kinase 2)
Diseases named in the same sentence as ERBB2 in open-access papers (continued):
Sharing a sentence is not in itself a finding about the gene and the disease.
cancer (continued). "The most commonly mutated region of ERBB2 in all cancer types is the kinase domain (66%), followed by the extracellular domain (26%), and lastly the transmembrane/juxtamembrane domain (8%)." (PMID 35181666, 2022). "The association between clinical outcomes and ERBB2 expression was analysed across various cancer types using TCGA data." (PMID 35990657, 2022). "Five patients harboring a programmed death ligand 1/2 (PD-L1/-L2) amplification, TMB-high, breast cancer gene 2 (BRCA2) mutation or ERBB2 amplification were treated with each investigational drug." (PMID 36119486, 2022). "Somatic activating mutations of ERBB2 have also recently been identified as contributors to the development of cancer." (PMID 36291943, 2022). "In the present cross-sectional study, we explored the mutational landscape of ERBB2 in 14,956 pan-cancer patients." (PMID 35911441, 2022). "Abnormal EGFR and ErbB2 activation can be observed in a wide range of mechanisms like overexpression, gene mutations, and autocrinergic stimulation in cancers." (PMID 36438839, 2022). "An infusion of 1010 anti-ERBB2 CAR T cells attempted to treat a patient with metastatic ERBB2+ cancer caused acute respiratory distress and the subsequent death of the patient." (PMID 35071966, 2022). "To assess the therapeutic benefit of patients with a ERBB2 mutation, we also compared the ERBB2 gene difference in the various pathological stages of cancer." (PMID 36172165, 2022). "A cancer type with ERBB2 deficiency, KICH presents fewer macrophages, mast cells, NK cells, Th2 cells, and follicular helper T cell cluster infiltration, apparently driving follicular B helper T cell-mediated adaptive immunity." (PMID 36172165, 2022). "The ERBB2 gene encodes a receptor tyrosine kinase whose expression and activation play a role in different types of human cancers." (PMID 36472635, 2022). "HER2, a transmembrane tyrosine kinase receptor encoded by the ERBB2 gene on chromosome 17q12, is a predictive and prognostic biomarker for breast, gastric and other cancers." (PMID 36236459, 2022). "Previously, two distinct mechanisms have been reported by which ERBB2 ECD variants activate certain cellular processes associated with cancer, i.e., the formation of disulfide-linked dimers and an increase in C-terminal phosphorylation." (PMID 34997908, 2022). "Targeted gene mutation analysis using a comprehensive cancer panel (Qiagen) revealed pathogenic genomic DNA alterations in ERBB2 (c.929C > T, p.S310F) in EMPD-PDXs." (PMID 35884581, 2022). "Among several cancers in which ERBB2 mutation occurred most common, we investigated the genetic variation spectrum." (PMID 35911441, 2022). "Preclinical and clinical investigations have shown the differential activity of some irreversible pan-HER TKIs such as afatinib, dacomitinib, and neratinib in targeting various ERBB2 mutant alleles across cancer types." (PMID 36686783, 2022). "Epidermal growth factor receptor 2 (ErbB2) is a potent oncogene associated with many cancers, including breast cancer, and its increased expression has been seen in the poor prognosis of cancer." (PMID 35990198, 2022). "Monoclonal antibody chemotherapy involves the injection of antibodies that locate and disrupt receptors associated with cancer, such as ErbB-2-targeting trastuzumab and EpCAM/CD326-targeting adecatumumab." (PMID 35208277, 2022). "In conclusion, we revealed a pan-cancer molecular landscape of ERBB2 amplification and mutations, and patients with ERBB2 alterations had higher TMB." (PMID 35911441, 2022). "It was shown that the survival of cancer patients was associated with pathological stages and ERBB2 gene overexpression." (PMID 36172165, 2022).
cancer (continued). "In the ERBB2 mutation primary tumors, we detected cancer-associated fibroblast infiltration through the four estimation algorithms, including EPIC, MCP counter, Xcell, and TIDE." (PMID 36172165, 2022). "It has been demonstrated that ERBB2 is involved in a series of cancer-associated processes, such as cell proliferation, cell survival, and differentiation." (PMID 35723337, 2022). "The present results are consistent with a previous study using PDX tumors harboring pathogenic ERBB2 mutations in other cancers." (PMID 35884581, 2022). "This is the most extensively investigated ERBB2 polymorphism related to cancer risk and is located at codon 655 (ATC/isoleucine to GTC/valine) in the transmembrane domain of the HER2 receptor (exon 17)." (PMID 35884448, 2022). "Nevertheless, significant differences were observed across distinct HER2-low subgroups (score 1+ versus score 2+) with ERBB2 mutations uniquely observed in score 2+ carcinomas." (PMID 36038884, 2022). "Scoring criteria used in other carcinomas in which ERBB2 has a pathogenic role (breast and gastroesophageal) can produce false results, as some differences in ERBB2 expression have been noted." (PMID 35954382, 2022). "ERBB2/HER2 is a novel susceptibility locus which contributes to cancer risk in combination with additional risk alleles." (PMID 34209587, 2021). "The ERBB2 gene is a tyrosine kinase receptor (also known as HER2) that is frequently amplified or mutated in cancer." (PMID 34209587, 2021). "Analysis of targeted sequencing of ERBB2 in multiple disease and control cohorts revealed that rare germline ERBB2 coding variants are more frequently associated with MPN compared to other hematologic malignancies as well as non-cancer controls." (PMID 34209587, 2021). "Western blot analysis indicated that several cancer hallmark pathways were suppressed following genetic Rlip depletion in tumors obtained from PyVT and Erbb2 GEMMs." (PMID 34283045, 2021). "We have previously identified α2,6-linked sialic acid (α2,6NeuAc), a cancer-associated negatively charged monosaccharide residue, as a major glycan signature within the receptor’s glycosylation landscape in ErbB2-driven GC cells." (PMID 33947960, 2021). "Because ZFP36/TTP is deficient in abundance and activity-in cancer cells, including invasive ductal breast cancer, over-expression of ERBB2-positive genes is further augmented by prolonged mRNA stability and increased translation." (PMID 34535639, 2021). "In vitro analyses have demonstrated that some ERBB2 mutations are oncogenic and promote cancer cell growth, invasion, and survival." (PMID 34257600, 2021). "miRNA-7 expression leads to significant loss of ERBB2 in the cardiomyocytes instead of the EGFR that is observed in cancer cells." (PMID 34759299, 2021). "The ERBB2 gene is a novel susceptibility locus which likely contributes to cancer risk in combination with additional risk alleles." (PMID 34209587, 2021). "Mutations and high‐level amplifications of cancer‐critical genes, the latter including ERBB2 and EGFR, were predominantly homogeneous within patients." (PMID 33325154, 2021). "We observed NNC and NIC isoforms involving cancer-associated genes such as ERBB2 and CD44 and confirmed previously known FSM isoforms associated with these two genes." (PMID 33482911, 2021). "A point mutation in ERBB2 (a member of tyrosine kinase receptor) which is involved amplification of cancers was also observed." (PMID 34204435, 2021). "Somatic mutations in ERBB2/3 (HER2/3) were found in a wide range of cancers 54, and lead to constitutive HER2/3 activation." (PMID 33570867, 2021). "Given the HER2-receptor’s prominent role in the etiology of the HER2-subtype, we also examined the ERBB2 (encoding the HER2-receptor) expression across the cancer clusters." (PMID 34650042, 2021). "Over-expression of ERBB2 in cancer is strongly linked to the cancer invasive capacity and patient’s survival." (PMID 34535639, 2021).
cancer (continued). "It is known that cancer treatment resistance can be caused by the pro-cell survival role of autophagy and by ERBB2 expression." (PMID 33801244, 2021). "Human epidermal growth factor receptor 2 (HER2), the protein encoded by the Erb-b2 receptor tyrosine kinase 2 (ERBB2) gene, is one of the main therapeutic targets in human cancers." (PMID 33710417, 2021). "Overexpression of members of the HER/erbB transmembrane tyrosine kinase family like HER2/erbB2/neu is associated with various cancers." (PMID 33572976, 2021). "In preclinical studies, increased levels of ErbB2/HER2 were associated with treatment resistance to cetuximab in several different cancer lines including SCCHN cell lines." (PMID 34298761, 2021). "ERBB2 is a member of the ErbB receptor family, which is often overexpressed, amplified or mutated in various cancer types." (PMID 33298978, 2020). "Evidence have been accumulated on the role of ERBB2 amplification in cancer, while very little is known on the role of point mutations." (PMID 32332709, 2020). "Somatic activating mutations of ERBB2 represent a well-described mechanism driving oncogenesis in several cancer types." (PMID 32295625, 2020). "Signal cascades leading to the synthesis of DNA and cellular proliferation involving receptor tyrosine kinases such as ErbB2 (HER2/Neu), ErbB3, and ErbB4 are implicated in cancer cell proliferation and tumorigenesis." (PMID 32752229, 2020). "Nevertheless, the seemingly unavoidable resistance to the therapeutic agents against ErbB2 was acquired by cancer cells in most cases through diverse mechanisms, which include mutations occurring in ErbB2 that abrogate antibody or inhibitor binding." (PMID 32327714, 2020). "HER2 (ERBB2) is overexpressed in various human cancers and is associated with poor patient survival." (PMID 32754598, 2020). "ErbB2 plays a central role in cancer cell invasiveness, and is associated with cytoskeletal reorganization." (PMID 32714928, 2020). "It has been pointed out by several studies that mutations of ctDNA ERBB2 correlated with HER2‐targeted resistance in cancer." (PMID 33377634, 2020). "The beneficial effect of ErbB2 in differentiated tissues contrasts with the consequences of its overexpression, which is associated with cancer." (PMID 32655416, 2020). "Trastuzumab specifically recognizes cells expressing the HER2 receptors (only cancer cells express HER2 in significant quantities) encoded by the ErbB2 gene." (PMID 33023024, 2020). "In the ERBB2 network, we also found a subnetwork of direct protein–protein interactions formed by the non-SMC condensin I complexes (NCAPD2, NCAPG, NCAPH), a vital complex associated with the ERBB2 signaling pathway and cancer development." (PMID 33424936, 2020). "The advent of next-generation sequencing technologies has enabled the identification of ERBB2/HER2 point mutations in various cancers." (PMID 32366937, 2020). "We used the crystal structures of the EGFR, ErbB2, ErbB3, and ErbB4 kinases that constitute this family to perform rigidity decomposition and then align the positions of the predicted cancer driver mutations with the structural mobility maps." (PMID 31245384, 2019). "Overexpression of ErbB1 and/or ErbB2 has been implicated in the development and progression of various cancer types such as head and neck, lung, pancreas, bladder, breast, colon, ovary and bladder." (PMID 31905843, 2019). "High expression levels of EGFR and ErbB2 has been implicated in the development of various types of cancers including breast, lung, colorectal, ovarian, prostate, head and neck." (PMID 30688116, 2019). "While the majority of somatic mutations in the EGFR and ErbB2 kinases increase the kinase activity, a number of the classified ErbB4 cancer mutants have been shown to inhibit or reduce the kinase activity." (PMID 31245384, 2019).
cancer (continued). "Using mouse models, we demonstrated that Erbb2 deficiency prevented lung tumor development induced by deletion of Pten and Smad4 by de-dysregulation of these cancer-related genes." (PMID 31248101, 2019). "MUC4 is associated with changes in ErbB2 expression, apoptosis, proliferation, differentiation, and some cancers." (PMID 31744086, 2019). "Several empirical studies showed that Grb7 associates with ERBB2 and facilitates ERBB2-mediated cancer migration and proliferation." (PMID 31083325, 2019). "The expression heatmap of these overlapped genes further demonstrates that Erbb2 loss normalized the expression patterns of cancer-related genes." (PMID 31248101, 2019). "Recently, The Cancer Genome Atlas project reported mutation or amplification of ERBB2 in a subset of human iUC." (PMID 29699519, 2018). "In conclusion, our data advocate for an enlargement of the screening of ERBB2 mutations and amplifications beyond breast or oesogastric cancers." (PMID 29515767, 2018). "Previous studies reported that NRG1 exerts its effects in cancers by directly binding to ERBB3 or ERBB4 which heterodimerizes with ERBB2 and the ligand-receptor interaction, causes the phosphorylation of receptors and activation of signaling cascades." (PMID 30486894, 2018). "It is reported that TAK 165 is a selective inhibitor of ERBB2, a receptor tyrosine kinase often amplified or mutated in several cancers." (PMID 30392977, 2018). "To this end, we examined the selectivity of ganetespib-induced anti-proliferative effects in ErbB2+ cancer by overexpressing ErbB2 in two cancer cell lines that are typically ErbB2 deficient (MDA-MB-435 and MCF7)." (PMID 29717218, 2018). "MiR-3622b-5p made ERBB2-positive cancer cells more susceptible to the apoptosis induced by cisplatin and 5-fluorouracil." (PMID 28160563, 2017). "Gene amplification causes ligand-independent homo-dimerization of ErbB2, which stimulates cancer cell proliferation." (PMID 28900130, 2017). "Use of mTOR inhibitors in combination with trastuzumab or lapatinib is currently underway for cancers that are refractory to the anti-ERBB2 therapy, mostly caused by aberrant PI3K/Akt/mTOR signaling." (PMID 29050229, 2017). "ER/PgR‐negative cancer and ErbB2‐positive cancer, defined as ErbB2‐enriched, are associated with more aggressive disease and poor prognosis in the absence of effective treatment." (PMID 28781955, 2017). "At present, the underlying mechanisms of ERBB2 rendering cancer cells chemoresistance remain largely unclear." (PMID 29163776, 2017). "The oncogenic Erbb2 is involved in the development of various cancer types and its over-expression is associated with an earlier recurrence and shortened survival." (PMID 28473715, 2017). "Mutations in CDH1 (OR=0.12, CI=0.034–0.38) and ERBB2 (OR=0.16, CI=0.042–0.59) were uncommon in ER− cancers, but were associated with lower grade." (PMID 27161491, 2016). "Conversely, increased ErbB2 expression causes cancer resistance to ErbB1-directed therapies, e.g., cetuximab that specifically targets ErbB1." (PMID 27286447, 2016). "ERBB2 overexpression is associated with increased cancer cell metastasis, invasion, angiogenesis, and survival." (PMID 27007654, 2016). "For example, increased ErbB2 expression causes resistance of ErbB1-overexpressing cancer cells to cetuximab which specifically targets ErbB1." (PMID 27286447, 2016).
cancer (continued). "In cancer, amplification of the ErbB2 gene, encoding the subunit of the heterodimeric NRG1-receptor with high kinase activity induces constitutively high protein levels." (PMID 27175488, 2016). "Hotspot missense mutations on known cancer genes such as ERBB2 and KRAS were largely observed as region-specific aberrations." (PMID 27175599, 2016). "ErbB1 and ErbB2 are oncogenic cell surface receptor tyrosine kinases, linked to many forms of human cancer, and are major cancer therapeutic targets." (PMID 27286447, 2016). "EGFR (ERBB1) and HER2 (ERBB2) are members of a tyrosine kinase receptor family frequently activated in cancer either by receptor overexpression or mutations." (PMID 27387915, 2016). "Expression of Rab25 was associated with significant increases in ErbB2 protein levels in a panel of difference cancer cell lines including A2780, SKOV3, A549 and U251 cell lines." (PMID 26967059, 2016). "In conclusion, by showing that NRG1-dependent ErbB2–ErbB3 signalling is essential for the survival of differentiated trophoblast cell populations, we newly identify a physiological role for this cancer-associated receptor combination during human development." (PMID 26490994, 2015). "The most investigated ERBB2 polymorphism related to cancer risk is I655V (rs1136201) located at the codon 655 (ATC/isoleucine to GTC/valine) in the transmembrane domain of the receptor." (PMID 25699077, 2015). "The overexpression of ERBB2 has been reported to be associated with different types of malignant tumors in several studies." (PMID 25889298, 2015). "For example, EGFR and ErbB2 are mutated in many epithelial tumors and clinical studies suggest that they play an important role in cancer development and progression." (PMID 26635612, 2015). "Nine (75.0%) of the 12 cancers with the −815A>T variant were ER+ and ERBB2− (the remaining three were ER–/ERBB2–) as compared with 553 (63.2%) out of the 874 cancers that did not harbor −815A>T (P = 0.551)." (PMID 25036186, 2014). "To conclude, we have used combinatorial protein engineering together with phage- and cell-display technology to design, evolve and evaluate new minimal binding proteins based on an albumin-binding domain toward the cancer-associated ERBB2." (PMID 25089830, 2014). "Two candidates with strong regulatory effects emerging from our analysis are components of growth factor receptors, and implicated in cancer development, namely ERBB2 and FGFR2." (PMID 23737949, 2013). "Mutation or overexpression of EGFRs (well documented for ErbB1 and ErbB2), including through gene amplification (e.g., for HER2/ERBB2) are often associated with a poor prognosis in cancer patients." (PMID 23531534, 2013). "It has been reported that treatment with trastuzumab, a humanized anti-ErbB2 mAb, reduces the growth of cultured cancer cells by disturbing an associated signaling pathway." (PMID 23638030, 2013). "HER2+ cancers are frequently associated with amplification and over-expression of the ERBB2 and GRB7 genes, both from the 17q12–21 amplicon." (PMID 22343619, 2012). "The association of human ErbB2 transmembrane polymorphism (codon 655) with cancer is also consistent with this role." (PMID 22279592, 2012). "erbB2 overexpression was, indeed, found in various cancers (including breast, ovarian, and endometrial) to be associated with cancer cell proliferation, poor survival, and resistance to therapy." (PMID 21876697, 2011). "Her2 mutations are relatively rare in human cancers; however wild type ErbB2 is amplified at the genomic level or overexpressed at the protein level in approximately 30% of invasive ductal breast cancers." (PMID 21272329, 2011). "Conversely, CB2 receptor staining was evident in 72% of the carcinomas (63/87) and it was significantly associated with ErbB2 expression, since it was observed in 91% of the ErbB2-positive tumors (21/23, p = 0.018)." (PMID 20649976, 2010).